IL6 (interleukin 6)
Diseases named in the same sentence as IL6 in open-access papers (continued):
Sharing a sentence is not in itself a finding about the gene and the disease.
cerebral edema (27 papers, 2011 to 2025). "GAL3 levels on admission are a possible predictor of in-hospital mortality after OHCA and are associated with cerebral edema and IL-6 driven inflammation." (PMID 40821008, 2025). "TBI-induced microglial activation and increased expression of inflammatory mediators (HMGB1, TNF-α, IL-1β, IL-6) in the brain have been associated with cerebral edema and neurological deficits." (PMID 32610502, 2020). "IL-6, which is produced by neurons, microglia, astrocytes and recruited macrophages in response to viral CNS infection, causes an increased permeability of the blood brain barrier, which leads to interstitial cerebral edema, and raised intracranial pressure." (PMID 25886645, 2015). "After brain injury, the expression of TNF-α, IL-6, IL-1β, and other inflammatory factors is up-regulated, which is closely related to the development of cerebral edema." (PMID 40584448, 2025). "In this study, elevated levels of interleukin-6 were significantly noted in all cases involving fulminant cerebral edema and acute necrotizing encephalopathy." (PMID 38178046, 2024). "Other inflammatory cytokines such as IL-6 and IL-1β and NF-κB activation play an important role in the pathogenesis of brain edema." (PMID 34795593, 2021). "We wanted to know if miR-7-5p is also associated with MMP-9, ZO-1, occludin, TNF-α, IL-6, NLR, and CRP and if it jointly affects brain edema." (PMID 33392188, 2020). "Inflammatory cells release pro-inflammatory cytokines (e.g., TNF-α, IL-1β, IL-6), chemokines, and reactive oxygen species (ROS), which further exacerbate neuronal apoptosis, blood-brain barrier disruption, and cerebral edema, and aggravate neurological deficits." (PMID 41451361, 2025). "The release of interleukin 6 (IL-6) and C-reactive protein is involved in the inflammatory cascade and leads to the increased permeability of the blood–brain-barrier, which is responsible for development of cerebral edema." (PMID 38137130, 2023). "The primary outcome is the dichotomized Glasgow Outcome Score at 6 months and 12 months after injury, and the secondary outcomes are the Glasgow Coma Scale, the volume of traumatic brain edema, the serum levels of C-reactive protein and interleukin-6, and the Modified Barthel Index." (PMID 35212308, 2022). "The increase of TNF-α and IL-6 levels may increase the accumulation of Glx in astrocytes and promote the occurrence of cerebral edema." (PMID 34630618, 2021). "Moreover, it inhibited NF-κB DNA-binding activity, reduced expression of inflammatory molecules (TNF-α, IL-1β, IL-6) and ameliorated locomotor function as evident by beam walking performance, along with cerebral edema and cortical apoptotic cell death." (PMID 32610502, 2020). "After traumatic brain injury (TBI), Cerebrolysin enhances neurological scores, lowers cerebral edema, improves BBB permeability, and reduces inflammatory cytokines such as TNF-α, IL-1β, IL-6, and NF-κB." (PMID 40362194, 2025). "While IL-6 enhances neurogenesis and wound healing in TBI animal models, it can also lead to breakdowns in the blood–brain barrier (BBB) and exacerbate cerebral edema." (PMID 38474264, 2024). "After TBI, inflammatory factors such as TNF-α, IL-1, and IL-6 are secreted and can induce oxidative stress responses and apoptosis, resulting in blood-brain barrier (BBB) impairment and cerebral oedema." (PMID 33381552, 2020). "CCHF infection can cause endothelial cell dysfunction (with increased vascular permeability) through the induction of cytokines (tumor necrosis factor-α, interleukin-6, interleukin-10, interferon [IFN]-γ), which can result in cerebral edema." (PMID 25529825, 2015). "IL-6 together with TNF can increase cerebral EC permeability, which could contribute to the cerebral oedema observed in CM." (PMID 21029292, 2011).
cerebral edema (continued). "We obtained preliminary conclusions from serum indicators of clinical patients that miR-7-5p may affect brain edema, but it does not affect MMP-9, ZO-1, occludin, IL-6, TNF-α, NLR, and CRP expression to affect the formation of brain edema." (PMID 33392188, 2020).
cyst (27 papers, 2007 to 2026). A sac-like closed membranous structure that may be empty or contain fluid or amorphous material. "IL6 has been previously implicated in VS, where it contributes to inflammatory signaling and correlates with tumor progression and cyst formation." (PMID 41231782, 2025). "On the other hand, IL-6 plays a protective role in chronic infection, as IL-6-deficient ME-49-infected mice show high numbers of cyst and mortality, with severe toxoplasmic encephalitis with areas of necrosis." (PMID 34610039, 2021). "The interplay of pro-inflammatory and anti-inflammatory mediators in ADPKD highlights a complex immune environment, where cytokines like IL-1β, IL-6, and IL-37 play key roles in cyst formation and inflammation regulation." (PMID 41431718, 2026). "Two positive feedback loops that integrate renal inflammation in cyst development were established: SMYD2/IL-6/STAT3/SMYD2 and SMYD2/TNF-α/NF-κB/SMYD2." (PMID 41431718, 2026). "There is rising evidence the cystic and solid tumor components of ACPs have high levels of IL-6 and the treatment using tocilizumab, an IL-6 inhibitor, resulted in a significant cyst shrinkage in two patients for whom it was offered." (PMID 37109772, 2023). "But during cyst establishment and growth, there is a switch to a Th2 response by secreted IL-4, IL-5, IL-6, IL-10 and so on, which is beneficial to parasite survival." (PMID 35360110, 2022). "When OK-432 is administered locally, inflammatory cells, such as neutrophils and monocytes, infiltrate the cyst and various cytokines, including IL-6, IL-8, IFN-γ, and TNF-α, are secreted." (PMID 27144039, 2016). "It has been reported that cystic growthmay be due to the autocrine stimulation of cyst epithelial cellproliferation by TNF-alpha and IL-6, and the osteolytic activityof these cytokines, causing local bone loss." (PMID 17497030, 2007). "Moreover, the VLP vaccine suppressed the production of IFN-γ and IL-6 cytokines, leading to a significant reduction in brain inflammation and decreased cyst counts following lethal challenge with T. gondii ME49 infection." (PMID 40872874, 2025). "To explore the molecular mechanism of cyst formation induced by the abnormal activity of IL-6/JAK/STAT3 signaling pathway, we focused on FOSL1, a target gene of the IL-6/JAK/STAT3 signaling pathway, whose gene expression was greatly increased in xCEP290 morphant kidney in our RNA-seq analysis." (PMID 40570958, 2025). "In terms of cyst size and cyst volume, IL6 expression was positively correlated with cyst size (r = 0.22, P = 0.013) and cyst volume (r = 0.25, P = 0.005), and IL10 expression was also positively correlated with the cyst size (r = 0.24, P = 0.006) and cyst volume (r = 0.26, P = 0.002)." (PMID 38965454, 2024). "The results showed that EgCF treatment significantly downregulated the expression of pro-inflammatory cytokines IL-6 and TNF-α in macrophages, similar to the cyst fluid of E. multilocularis." (PMID 37689671, 2023). "VLP-immunized mice showed a significant reduction of cyst counts and lower levels of pro-inflammatory cytokines (IFN-γ, IL-6) production in the brain upon T. gondii ME49 challenge infection compared to unimmunized control." (PMID 37104285, 2023). "These include IFN-γ, IL-6, and TNF-α, all of which have been found by others and us to be elevated in murine models of PKD or ADPKD patient cyst fluid." (PMID 36422996, 2023). "Further, cytokines such as interferon-gamma (IFN-γ), interleukin-6 (IL-6), IL-12b, and tumor necrosis factor (TNF) are considered signatures of T. gondii infection in the CNS of mice and have been positively correlated with cyst load and behavior." (PMID 35857765, 2022). "It has been suggested that IL-6 and TNF-α have a local “protector” role in gross cystic disease and may be used as a marker to identify cyst type." (PMID 27293305, 2016). "However, how IL-6 signaling is involved in cyst formation of NPH as well as other cystic diseases has not been elucidated thus far." (PMID 40570958, 2025).
cyst (continued). "In this study, we had not systematically investigated the effects of iron on macrophage polarization, but we found there were higher expressions of IL8 and VEGF, lower expressions of TNFα and CCL2, and no change in IL1b and IL6 in the macrophages treated with cyst fluid and iron." (PMID 36547083, 2022).
keratitis (27 papers, 2010 to 2025). A corneal disease that is characterized by inflammation of the cornea. "In vivo, CRAMP−/− mice show increased susceptibility to Pseudomonas aeruginosa (PA) keratitis and enhanced secretion of pro-inflammatory cytokines, including IL-1β, IL-6 and TNF, in PA-infected corneas." (PMID 33468624, 2021). "Increased proteolytic activity has been reported to be upregulated in patients with corneal melting, infectious keratitis, and corneal burning and are linked to epithelial barrier dysfunction, as well as an excessive inflammatory response by the activation of IL6." (PMID 37108070, 2023). "The minor IL6 C allele of rs1800795 and T allele of rs1800797 were associated with a greater risk of microbial keratitis compared with sterile keratitis and controls combined, and the dominant haplotype GGC was associated with a lower risk of microbial keratitis." (PMID 36422638, 2022). "IL6, the most outstanding hub gene, which had been reported to play an important role in ocular surface immune defense and decreases the severity and susceptibility of contact lens–related keratitis." (PMID 32016117, 2020). "IL-1β, IL-6, and IL-8 can exhibit synergistic effects in the development of keratitis, eliminating pathogens and further mediating adaptive immune response." (PMID 39869570, 2025). "The impact of PL on the expression of HMGB1, LOX-1, TNF-α, IL-1β, IL-6, IL-10 and ROS in A. fumigatus keratitis was investigated using RT-PCR, ELISA, Western blot, and Reactive oxygen species (ROS) assay." (PMID 38655086, 2024). "In the S. aureus keratitis study, treatment with genipin revealed a significant downregulation of IL6, TNFα, and interferon γ (IFNɣ) compared to the vehicle-treated group (p = 0.001 for IL6, p = 0.008 for TNFα, p= 0.025 for IFNɣ)." (PMID 37108070, 2023). "Some scholars have found that LXA4 attenuates the inflammatory response by downregulating the production of the proinflammatory factors IL-1β, TNF-α, and IL-6 via the Fpr2 receptor in Aspergillus fumigatus keratitis mouse models." (PMID 36544058, 2023). "Even though the statistical power would have been reduced due to a decrease in the sample size, one SNP in IL6 occurred significantly more frequently in cases of sterile keratitis than in controls." (PMID 36422638, 2022). "This implies a possible contribution to ethnicity in the role of IL-6 in keratitis, or a different role of IL-6 in different forms of keratitis." (PMID 36422638, 2022). "There was an association between a potentially deleterious missense SNP in the IL-6 signal transducer rs2228046 and keratitis in a small pilot study." (PMID 36422638, 2022). "The ocular response against infectious keratitis induces the secretion of several inflammatory cytokines, such as IL-1a, IL-1β, IL-6, IL-8, tumor necrosis factor α, and the infiltration of immune cells at the site of infection." (PMID 34436544, 2021). "In studies of animal models on the herpes simplex virus-infected keratitis, cytokines such as IL-1β, IL-6, IL-8, IL-10, IL-12, and IFN-γ were demonstrated to play a predominant role in disease development." (PMID 29673332, 2018). "Increased IL-1β and IL-6 are the specific inflammatory signals for keratohelcosis and keratitis." (PMID 29673332, 2018). "Moreover, Il6 and Il1b expressions, which contribute to S. aureus clearance in skin wound sites and in keratitis, were significantly higher in miR‐223Y/− wounds." (PMID 30171089, 2018). "Among three corticosteroids, PA showed the least influence on keratocytes in normal condition and it significantly decreased IL-6 level and maintained collagen synthesis in LPS-induced keratocytes, which is suggested as an anti-inflammatory drug treatment at the early stage of keratitis." (PMID 28448563, 2017). "Taken together, the findings of our study indicate that the interaction of PRRs and A. fumigatus could be concerned with irreversible change of keratitis via cytokine expression such as IL-6 and IL-1β in concert with IDO expression." (PMID 26361229, 2015).
keratitis (continued). "Silencing viral microRNA targets as a novel antiviral therapy, our result may imply that in diseased tissue like keratitis, using miR-H6 could not only suppress viral replication, but also decrease inflammation due to IL-6 production." (PMID 22550533, 2012). "Similarly, there were higher levels of IL-1β, IL-6 and IL-8 cytokines were quantified in keratitis caused by Gram-negative bacteria." (PMID 33208864, 2020). "All the mice suffered keratitis, severe corneal opacity and ELISA results indicated HE4 overexpression, and significantly increased IL-6 and TNF-α levels in the cornea." (PMID 41883385, 2025). "If the circulating concentration of IL-6 is reduced by the minor alleles or genotypes in rs1800795 and rs10499563 in the current population, this appears to be not directly associated with the risk of keratitis, as the SNPs were associated with decreased and increased risk of MK, respectively." (PMID 36422638, 2022). "Certain SNPs in IL6, CXCL8, and IL12B occurred less frequently in all keratitis cases than in controls." (PMID 36422638, 2022). "H-RN inhibited IL-6, monocyte chemotactic protein-1(MCP-1), Interferon- γ(IFN-γ), and ICAM-1 expression triggered by LPS or poly(I:C), alleviated the clinical manifestation and reduced the clinical score in keratitis in vivo." (PMID 28125988, 2017). "During corneal infections, IL-1β, IL-6, IL-8, and TNFα are important in the initiation of inflammatory signals and both TLR2 and TLR5 mediate microbial clearance and cytokine production during S. aureus and PA keratitis." (PMID 28796783, 2017). "Furthermore, our in vivo and in vitro data indicated that STING decreased the stromal infiltration of immune cells and the production of inflammatory cytokines including IL-1β, IL-6, MIP-2, and TNF-α, suggesting that STING plays an anti-inflammatory function in PA-induced keratitis." (PMID 29922287, 2018).
Listeria infection (27 papers, 2012 to 2024). "Surprisingly, chronic infection with MHV68 complemented the immunodeficiency of HOIL-1, IL-6, Caspase-1 and Caspase-1;Caspase-11-deficient mice following Listeria infection." (PMID 25599590, 2015). "IL-6, Caspase-1 and Caspase-1;Caspase-11-deficient mice were also protected from lethality following Listeria infection by chronic MHV68 infection." (PMID 25599590, 2015). "We further show that chronic infection with MHV68 rescued HOIL-1, IL-6, Caspase-1 and Caspase-1;Caspase-11-deficient mice from lethal Listeria infection, thereby masking the genetic immunodeficiency observed in MHV68-negative mice." (PMID 25599590, 2015). "Considering the reduced Th17 immunocompetency as the main risk factor of listeriosis, biomarkers of poor prognosis, such as high sensitivity to hypervirulent Listeria clones, low IL-17A/IL-6 ratios, and anti-GAPDH1–22 antibodies should assist in reducing listeriosis incidence." (PMID 27965668, 2016). "InlH from the serovar 1/2a EGD-e strain has been reported to mediate IL-6 secretion during murine listeriosis." (PMID 35223532, 2021). "Cytokines such as TNFα, IL-6, IL-8 play an important role in the control of listeriosis by neutrophil recruitment in mice." (PMID 28467447, 2017). "We observed that neonatal listeriosis patients also presented low TNF-α/IL-6 ratios, indicating predominant Th2 immune responses." (PMID 28903312, 2017). "A predominant Th2 cytokine profile with low Th1-Th17/IL-6 ratios, is also a biomarker of poor prognosis in adult listeriosis because it favours bacterial growth." (PMID 28903312, 2017). "We also observed that GAPDH1–22-activated MoDC from listeriosis patients with cancer released high levels of TNF-α while low levels of IL-6 and IL-10, suggesting a shifting toward Th1 pattern." (PMID 27965668, 2016). "Vaccination of systemic listeriosis reduced IL-6 levels (Th2 pattern) and presented a significant increase in IL-12 levels (Th1 pattern)." (PMID 28335280, 2016). "Here, we report that GAPDH1–22 epitopes can activate MoDC of listeriosis patients with cancer receiving chemotherapy to release high levels TNF-α while low production of IL-6 and IL-10, a clear Th1 cytokine pattern." (PMID 27965668, 2016). "We confirmed that induction of Tnf and Il6 mRNA was significantly impaired following Listeria infection in vivo by measuring cytokine transcripts in peritoneal cells from mice 3 to 12 hr after infection." (PMID 25599590, 2015). "Innate immunity to Listeria in mice depends on tissue-resident macrophages and CD8α+ dendritic cells responding to Listeria infection by secreting pro-inflammatory cytokines including TNFα, IL-12, and IL-6." (PMID 25599590, 2015). "In listeriosis, the protective effect of endogenous IL-6, which is mainly produced by resident hepatic macrophages, i.e. Kupffer cells, includes a more effective control of Lm in the liver as well as increased neutrophilia." (PMID 23825949, 2013). "Neutralization of IL-6 in otherwise protected Cyld−/− mice resulted in failure to control Lm and death from listeriosis." (PMID 23825949, 2013). "Therefore, we demonstrate that mast cell TLR2 plays a crucial role in regulating the synthesis of IL-6 and IL-13 during Listeria monocytogenes infection in MC." (PMID 34194428, 2021). "Interferons (IFNs) and pro-inflammatory cytokines like IL6 were additionally reported to play crucial roles during Listeria infection that might be connected to SOCS proteins in the Listeria infected system." (PMID 33585275, 2020). "Efficient vaccine vectors in listeriosis are expected to control pathogen dissemination to the CNS and liver, and release protective cytokines such as IL-12p40, while showing basal levels of acute anti-inflammatory cytokines such as IL-6." (PMID 28903312, 2017). "In addition, listeriosis patients with cancer present low IL-17A/IL-6 ratios and significantly reduced levels of anti-GAPDH1–22 antibodies, identified as two novel biomarkers of poor prognosis." (PMID 27965668, 2016).